RNF213 (ring finger protein 213)
Diseases named in the same sentence as RNF213 in open-access papers (continued):
Sharing a sentence is not in itself a finding about the gene and the disease.
Headache (1 paper, 2023). Cephalgia, or pain sensed in various parts of the head, not confined to the area of distribution of any nerve. "Single-nucleotide polymorphism rs8072917 of gene RNF213 was the causal variant for broadly defined headaches, which was also associated with cellulitis, neck and face abscesses and muscular symptoms." (PMID 37288313, 2023). "For broadly defined headache phenotype, we identified a locus on Chromosome 17, with the lead single-nucleotide polymorphism rs8072917 (odds ratio 1.08, P = 4.49 × 10−8), mapped to two protein-coding genes RNF213 and ENDOV." (PMID 37288313, 2023). "For broadly defined headache phenotype, an SNP cluster was identified in Chromosome 17 RNF213 gene region, of which five variants rs8078851, rs9674961, rs4890009, rs8080730 and rs4890010 are in high LD (R2 > 0.93) with the top SNP rs8072917 (with lowest P-value of 4.49 × 10−8)." (PMID 37288313, 2023). "We then conducted a conditional analysis and a statistical fine-mapping of the broadly defined headache-associated loci and identified a single credible set of loci with rs8072917 supporting that this lead variant was the true causal variant on RNF213 gene region." (PMID 37288313, 2023). "Among broadly defined headache phenotype, rs8072917 reached genome-wide statistical significance, and this SNP is in cis-acting regulatory elements of the RNF213 and ENDOV gene." (PMID 37288313, 2023). "For broadly defined headache phenotype, we found that SNPs located within Chromosome 17 were all mapped to protein-coding gene ring finger protein 213 (RNF213)." (PMID 37288313, 2023). "The replication of RNF213 identified in GWAS from Western countries validates our broadly defined headache definition and suggests a shared genetic basis across ethnic groups." (PMID 37288313, 2023). "RNF213 replicated the result of previous studies and played important roles in the biological mechanism of broadly defined headache." (PMID 37288313, 2023). "For broadly defined headache, the conditional analysis returned that no SNPs in high LD reach genome-wide significance of P < 5 × 10−8 within the risk loci RNF213 after conditioning on the lead variant rs8072917." (PMID 37288313, 2023). "Combining results from GWAS and FUMA together, we highlighted the role of RNF213 gene and ENDOV gene play in the biological mechanism of broadly defined headache." (PMID 37288313, 2023).
Intellectual disability (1 paper, 2025). "A Korean RNF213 Arg4810Lys and an AFF4 mutation (Pro253Leu) was reported along with CHOPS syndrome and MMD, developmental delay, short stature, synophrys, intellectual disability, and vascular abnormalities in renal arteries and the infrarenal aorta." (PMID 40869185, 2025). "RNF213 Arg4810Lys and KIF1A gene Ala85Asp coexistence was found in an atypical MMD case with gait disturbance, childhood epilepsy and intellectual disability, spastic paraplegia, and cerebellar atrophy." (PMID 40869185, 2025).
intracerebral hemorrhage (1 paper, 2023). A cerebrovascular disorder characterized by bleeding into one or both cerebral hemispheres including the basal ganglia and the cerebral cortex. "Across subtypes, the highest hit rate (HR) was intracerebral hemorrhage (ICH, 7/18 = 38.9%), particularly with the etiological subtype of structural vasculopathy (4/4 = 100%, PVs in ENG, KRIT1, PKD1, RNF213); followed by ischemic small vessel disease (SVD, 15/48 = 31.3%; PVs in NOTCH3, HTRA1, HBB)." (PMID 36580209, 2023).
intracranial artery disease (1 paper, 2020). "Consequently, RNF213 may also be involved in systemic artery diseases other than intracranial artery disease." (PMID 32686731, 2020).
Legius syndrome (1 paper, 2023). Legius syndrome, also known as NF1-like syndrome, is a rare, genetic skin pigmentation disorder characterized by multiple cafC)-au-lait macules with or without axillary or inguinal freckling. "Of note, a splicing variant in RNF213 was recently reported in a patient with SPRED1-related Legius syndrome and MMS, further supporting the association between RNF213 and a predisposition to moyamoya vasculopathy." (PMID 36980803, 2023).
mid-aortic syndrome (1 paper, 2023). "Nevertheless, in our cohort only one patient carrying two maternally inherited RNF213 variants in cis had mid-aortic syndrome (73577), indicating that extracranial arterial involvement may either represent chance associations or a mutation-specific phenotype." (PMID 37012328, 2023).
multiple endocrine neoplasia type 2A (1 paper, 2025). An autosomal dominant tumor predisposition disorder caused by pathogenic variants in the RET gene, characterized by an increased risk of medullary thyroid carcinoma, pheochromocytoma, and hyperparathyroidism. "Interestingly, a case of multiple endocrine neoplasia type 2A (MEN2A) with concurrent RNF213 and RET mutations demonstrated potential synergistic effects between genetic predisposition and catecholamine hypersecretion in intracranial stenosis development." (PMID 40508049, 2025).
multiple sclerosis (1 paper, 2025). A progressive autoimmune disorder affecting the central nervous system resulting in demyelination. "A higher RNF213 expression and pathogenic variants affecting transcription and activation of inflammatory mediators have also been described in familial cases of multiple sclerosis." (PMID 40507841, 2025).
neuroendocrine tumors (1 paper, 2020).
periodontitis (1 paper, 2025). An acute or chronic inflammatory process that affects the tissues that surround and support the teeth. "In the Periodontitis group, the most significant genes included CTTNBP2NL, SOS1, RNF213, and IL12RB2." (PMID 40458179, 2025).
psoriasis (1 paper, 2015). An autoimmune condition characterized by red, well-delineated plaques with silvery scales that are usually on the extensor surfaces and scalp. "Of the most psoriasis-specific DEGPs, the majority were induced by IL-17A (e.g., FERMT1, GLUL, SULT2B1); in contrast, the most non-specific DEGPs were not disproportionately induced by IL-17A and several were repressed (e.g., AKR1B10, RNF213, ISG15)." (PMID 26251673, 2015).
respiratory syncytial virus infections (1 paper, 2022). "An RNF213 ortholog also exists in mice, and Rnf213-deficient animals are more susceptible to L. monocytogenes and respiratory syncytial virus infections than their wild-type counterparts." (PMID 36154443, 2022).
Right ventricular hypertrophy (1 paper, 2021). In this case the right ventricle is more muscular than normal, causing a characteristic boot-shaped (coeur-en-sabot) appearance as seen on anterior- posterior chest x-rays. "Overexpression of the vascular endothelial cell-specific RNF213 mutant aggravated the hypoxia-induced PH phenotype (high right ventricular pressure, right ventricular hypertrophy, and pulmonary vascular muscularization)." (PMID 34753383, 2021).
Salmonella Infections (1 paper, 2024). Infections with bacteria of the genus SALMONELLA. "During Salmonella infection, host E3 ligase RNF213 catalyzes the ubiquitination of the lipid A moiety of bacterial lipopolysaccharide (LPS), which relies on the RZ-finger domain but not the RING domain of RNF213, thus triggering cell-autonomous immunity." (PMID 37470788, 2024).
Tourette syndrome (1 paper, 2023). A neurologic disorder caused by defective metabolism of the neurotransmitters in the brain. "RNF213 was reported as a candidate gene for Tourette’s syndrome." (PMID 37686052, 2023).
infection (27 papers, 2010 to 2026). The state of being infected such as from the introduction of a foreign agent such as serum, vaccine, antigenic substance or organism. "This review aims to summarize the recent research progress on the mechanisms of RNF213 in pathogenic infections, which will aid researchers in understanding the antimicrobial role of RNF213." (PMID 37655297, 2023). "All these studies underlined that RNF213 acts as an antimicrobial host defense effector in MA patients, possibly triggered by autoimmune responses, prior infection and/or inflammatory processes." (PMID 35562882, 2022). "Various factors have been reported to upregulate RNF213, and all of them were related to inflammation caused by mitochondrial dysfunction and infection." (PMID 34381413, 2021). "We found that DDAH1 counteracts infection by Listeria monocytogenes, likely via effects on NO production as a potential mechanism underlying the antilisterial activity of RNF213." (PMID 34804992, 2021). "To test whether the binding interface identified is important for the degradation of RNF213 by IpaH1.4 during infection, we generated S. flexneri expressing HA-tagged IpaH1.4 alleles and tested their ability to degrade RNF213." (PMID 40205224, 2025). "Strategies such as aggressive infection control, minimizing chronic inflammatory conditions, and reducing oxidative stress may help preserve vascular integrity in RNF213 variant carriers." (PMID 40869987, 2025). "In addition, RNF213 has been demonstrated to restrict the de novo infection and lytic reactivation of Kaposi’s sarcoma-associated herpesvirus (KSHV) by degrading Replication and Transcription Activator (RTA) through the ubiquitin–proteasome pathway." (PMID 40623121, 2025). "In case genetic variants in MMA patients cause a dysfunction of sGC or RNF213, vascular damage related to infection, dyslipidemia, and homocysteine may lead to chronic inflammation." (PMID 37273690, 2023). "RNF213 genetic variants in MMA patients may sustain an inflammation even after remission of the causative infection, which may lead to sustained impairment of the cGMP signaling pathway." (PMID 37273690, 2023). "It is reasonable to speculate that MA patients carrying RNF213 polymorphisms may exhibit a defective immune response to infections or may be more predisposed to autoimmune reactions." (PMID 35562882, 2022). "Patient mutations in RNF213 may sustain the inflammation even after resolution of the infection, and it causes sustained cGMP signaling impairment." (PMID 34381413, 2021). "The expression of Rnf213 was markedly increased in WT BMDMs in response to infection with A. baumannii, herpes simplex virus type 1 (HSV-1) and rabies virus (RABV) and in response to treatment with LPS, poly(I:C) and IFN-β." (PMID 40623121, 2025). "In summary, we discovered that IpaH1.4/2.5 can bind and ubiquitylate RNF213 in vitro and, when recombinantly expressed in cells, target RNF213 for degradation, which prevents LPS ubiquitylation upon infection with Salmonella Typhimurium." (PMID 40205224, 2025). "Only treatment with carfilzomib prevented degradation of RNF213 upon infection with Shigella, indicating that IpaH1.4-induced degradation of RNF213 is mediated by the proteasome, as is the case for other IpaH–host effector pairs." (PMID 40205224, 2025). "Our data revealed that RNF213 protein levels are drastically reduced upon infection with WT S. flexneri and that the deletion of mxiE partially restored RNF213 expression in infected cells." (PMID 39282383, 2025). "When infected with either WT bacteria or S. flexneri ΔipaH2.5, around 30% of the infected cells lost their GFP fluorescence at 5 h after infection, indicative of RNF213 degradation." (PMID 40205224, 2025). "(G) Quantification of RNF213 localizing to Ct inclusions during infection of unprimed and IFNγ-primed (100 U/mL) A549 cells at 24 hours post infection." (PMID 38358795, 2024).
infection (continued). "RNF213 has been reported to counteract infection not only with S. Typhimurium but also with Listeria monocytogenes, a Gram-positive bacterium that lacks LPS, implying functional diversity of RNF213." (PMID 37655297, 2023). "These numerous interactions with innate immunity genes suggested a role of RNF213 in response to infection." (PMID 35562882, 2022). "As far as the antimicrobial activity reported in vivo, it is likely that the overexpression of RNF213 prior to infection gives rise to the innate defense response." (PMID 35562882, 2022). "A few years later, emerging data pointed out the identification of RNF213 as a novel immune sensor, unveiling the link between MA and infection." (PMID 35562882, 2022). "Conversely, the reduced RNF213 expression levels promoted in vitro infection with different viruses." (PMID 35562882, 2022). "This is of particular relevance to understanding the role of inflammation or prior infection in human patients with inborn errors in RNF213." (PMID 34599178, 2021). "At 24, 48, and 72 h post infection with Listeria we observed a dramatic increase in bacterial burden in the spleen of Rnf213−/− animals compared to WT littermate controls, which increased over time." (PMID 34599178, 2021). "Knockdown of RNF213 led to a small but significant increase in infection compared to scrambled siRNA control, both in the presence or absence of IFN-I." (PMID 34599178, 2021). "For further work we decided to focus on DDAH1 and CYR61 given their strong downregulation upon RNF213 knockdown and potential role in the host response to infection." (PMID 34804992, 2021). "Given the protective function of RNF213 against Listeria, we wondered if RNF213 adopts a specific subcellular localization during infection." (PMID 34599178, 2021). "Without any link to MMD, two independent studies recently identified RNF213 as an antimicrobial protein that can bind to cytosolic Listeria and Salmonella and that is important to control infection in vitro and in vivo." (PMID 34804992, 2021). "Our infection experiments with Listeria in mice, which lack RNF213 corroborated the protective effect in vivo, showing a multi-log increase in the number of colony-forming units in liver and spleen over time compared to WT animals." (PMID 34599178, 2021). "To this end, we knocked down RNF213 by a pool of siRNAs (siRNF213) in HeLa cells, conditions that were previously shown to promote infection with Listeria monocytogenes, HSV-1 and CVB3." (PMID 34804992, 2021). "To quantify how many bacteria were targeted, we repeated the experiment with mCherry-expressing Listeria and found that on average approximately 40% of intracellular Listeria cocolocalized with RNF213 at 18 h post infection." (PMID 34599178, 2021). "Following the track of infection-like state in cells, it is known that Rnf213 is transcriptionally induced in endothelial cells via PKR (double-strand-RNA dependent protein kinase) after exposing the cells to IFNG." (PMID 32342250, 2020). "Moreover, the longer isoform of RNF213 can also directly target viral proteins to inhibit infection." (PMID 42305619, 2026). "In addition, the production of IFN-β in the brain was much lower in Rnf213–/– mice than in WT mice 20 hours after intravenous infection with A. baumannii." (PMID 40623121, 2025). "To directly test whether S. flexneri promotes proteasomal degradation of RNF213, we conducted infections in the presence of the proteasomal inhibitor MG132." (PMID 41313637, 2025). "To directly test whether S. flexneri promote proteasomal degradation of RNF213, we conducted infections in the presence of the proteasomal inhibitor MG132." (PMID 39282383, 2025). "In addition, the induction of Rnf213 expression by pathogen infection and ligand stimulation was significantly increased in mouse skin fibroblasts (MSFs)." (PMID 40623121, 2025). "The identification of RNF213 as an immune sensor revealed a causal link between MMD and infection." (PMID 40623121, 2025).
infection (continued). "RNF213-deficient mice were found to be more susceptible to RVFV, whereas mice overexpressing RNF213 in vivo showed increased resistance to RVFV and exhibited reduced symptoms of infection compared with controls." (PMID 37655297, 2023). "Furthermore, in vitro and in vivo infection assays with four different pathogens revealed an as yet undescribed, broad antimicrobial function of RNF213." (PMID 34599178, 2021). "Conversely, overexpression of RNF213 resulted in reduced infection." (PMID 34599178, 2021). "Here, we show that RNF213 oligomerization could depend on ISGylation of RNF213 and that the protein protects against infection with various pathogens." (PMID 34599178, 2021). "Our study highlights that RNF213 plays a fundamental role as an antimicrobial host defense effector which could be inappropriately triggered during autoimmune responses, prior infection and/or inflammation in MMD patients." (PMID 34599178, 2021). "Among the 1,451 genes whose expressions were specifically altered in CEF after infection, some were involved in immune-related functions, while others, such as the significantly upregulated SLBP, P2RX7, GGT5, and RNF213, could promote viral particle replication or enhance the effect of infection." (PMID 38299864, 2024). "RNF213 might exert its role in infection with M1-ubiquitin chain involved in NF-κB activation." (PMID 37655297, 2023). "We show that RNF213 has broad antimicrobial activity in vitro and in vivo, counteracting infection with Listeria monocytogenes, herpes simplex virus 1, human respiratory syncytial virus and coxsackievirus B3, and we observe a striking co-localization of RNF213 with intracellular bacteria." (PMID 34599178, 2021). "(F) Representative images of RNF213 localizing to inclusions of WT Ct, garD::GII, and cdu1::GII strains during infection of A549 cells primed with IFNγ (100 U/mL)." (PMID 38358795, 2024). "A recent study pointed out that RNF213, an ISG15 interactor, can act as a sensor for ISGylated proteins to counteract infection." (PMID 36605987, 2022). "It is interesting to note that several of these genes (IFIT5, LY96, RNF213 and EPST1) were previously identified in a study examining LPAI and HPAI infection in ducks and chickens." (PMID 35327988, 2022). "Similar to RNF213, a previous genome-wide siRNA screen ranked DDAH1 and CYR61 as protective host factors during infection with Listeria monocytogenes (further referred to as Listeria), a facultative intracellular bacterial model pathogen." (PMID 34804992, 2021). "Taken together, we showed that increasing the expression levels of RNF213 led to lower infection levels of HSV-1, CVB3, and Listeria in cultured cells, while reducing the levels of RNF213 promoted in vitro infection with these pathogens as well as RSV." (PMID 34599178, 2021). "Comparing viral pseudo-infection with bacterial pseudo-infection, the presence of LPS in MEF led to a 10-fold (p = 0.0330) induction of Rnf213." (PMID 32342250, 2020). "Most interestingly, we demonstrated that RNF213, through its binding to ISG15, has a broad antimicrobial activity in vitro and in vivo, counteracting infection against Listeria monocytogenes, human respiratory syncytial virus (RSV), coxsackievirus (CV) B3 and herpes simplex virus 1 (HSV-1)." (PMID 34804992, 2021). "In contrast, upon infection with S. flexneri ΔipaH1.4 no measurable RNF213 degradation occurred." (PMID 40205224, 2025). "This mutant is unable to escape from the vacuole of epithelial cells and when compared with the parental strain at 6 h post infection, we did not observe colocalization with RNF213, indicating that RNF213 likely targets a subset of cytosolic bacteria, as was recently shown for Salmonella65." (PMID 34599178, 2021). "Indeed, cells lacking RNF213 failed to ubiquilate LPS upon infection." (PMID 35562882, 2022).